LINC00844 (long independently transcribed non-coding RNA 844)
Synonyms: LOC102724768
Gene: Long non-coding RNA gene on chromosome 10 (58,967,778 to 59,066,396, forward strand). Ensembl gene ENSG00000237949.
Diseases named in the same sentence as LINC00844 in open-access papers:
LINC00844 is named in the same sentence as 7 diseases in open-access papers, as found by Europe PMC text mining. Sharing a sentence is not in itself a finding about the gene and the disease. The quoted sentences say what the papers report.
prostate carcinoma (2 papers, 2020). A carcinoma that arises from epithelial cells of the prostate gland. "LINC00844 expression is dramatically downregulated in prostate cancer, and functional studies have revealed the association between the aberrant expression of LINC00844 and prostate cancer cell invasion and metastasis." (PMID 32025371, 2020).
breast carcinoma (1 paper, 2017). "LINC00844 expression was also down-regulated in HCC and breast cancer." (PMID 28729955, 2017).
glioma (1 paper, 2022). A benign or malignant brain and spinal cord tumor that arises from glial cells (astrocytes, oligodendrocytes, ependymal cells). "LINC00844 also has a significant prognostic value in gliomas, with a high expression suggesting a favorable prognosis." (PMID 35832170, 2022).
hepatocellular carcinoma (1 paper, 2020). A malignant tumor that arises from hepatocytes. "However, the function and mechanism of action of LINC00844 in the pathogenesis of hepatocellular carcinoma (HCC) are poorly understood." (PMID 32025371, 2020).
tumor (3 papers, 2020). "Downregulation of LINC00844 is associated with poor clinical outcomes and suppressed tumor progression/metastasis in PC." (PMID 32591022, 2020). "LINC00844 has been documented to be decreased in malignant and metastatic PCa cells, and acts as a tumor suppressor in cancer progression and metastasis, which is in line with our findings." (PMID 31938018, 2020). "Lower expression of LINC00844 was closely correlated with multiple clinical pathological features including pathological stage (P = 0.0484), portal vein tumor thrombus (P = 0.0471) and TNM (P = 0.0187)." (PMID 32025371, 2020). "Based on these results, we suggest that LINC00844 may act as a tumour suppressor in HCC." (PMID 32025371, 2020). "In our study, the relative expression level of LINC00844 was detected in HCC tissues (n = 40) and their adjacent non-tumour tissues (n = 40) with RT-qPCR." (PMID 32025371, 2020).
LINC00844 also shares sentences with these, for which no sentence is quoted: cancer (1 paper); Usher syndrome type 1 (1).